RAC1 (Rac family small GTPase 1)
Diseases named in the same sentence as RAC1 in open-access papers (continued):
Sharing a sentence is not in itself a finding about the gene and the disease.
anaplastic large cell lymphoma (2 papers, 2015 to 2018). Anaplastic large cell lymphoma (ALCL) is a rare and aggressive peripheral T-cell non-Hodgkin lymphoma, belonging to the group of CD30-positive lymphoproliferative disorders, which affects lymph nodes and extranodal sites. "In future investigation Rac1 and Cdc42, which are members of cell motility-regulating proteins will be analyzed in galectin-8-mediated cell invasion in anaplastic large cell lymphoma." (PMID 25573487, 2015).
B-cell lymphomas (2 papers, 2015 to 2016). "An unexpected finding in this study was that FilGAP and /or FLNa scores were positively correlated with cytoplasmic Rac1 scores in B-cell lymphomas, which is inconsistent with idea that the FilGAP/FLNa system suppresses Rac1 activity 9–11." (PMID 25641953, 2015). "Although we are presently unable to provide an appropriate explanation for this observation, it appears that the regulatory mechanism for Rac1/FilGAP/FLNa axis may be very complex in B-cell lymphomas." (PMID 25641953, 2015).
cervical adenocarcinoma (2 papers, 2021 to 2024). An adenocarcinoma arising from the cervical epithelium. "Therefore, we conclude that overexpression of DTL enhanced cell motility and promoted tumor metastasis of cervical adenocarcinoma by regulating the RAC1-JNK-FOXO1 axis." (PMID 34635635, 2021).
chlamydial infection (2 papers, 2010 to 2021). "The robust level and extended duration of Rac1 activation could indicate a comparatively more extensive role of Rac1 in chlamydial infection." (PMID 33468693, 2021).
chondrosarcoma (2 papers, 2017 to 2018). A malignant cartilaginous matrix-producing mesenchymal neoplasm arising from the bone and soft tissue. "The dependent and independent pathways of EIF2α also regulate the invasion and motility of sw-1353 chondrosarcoma cells and the inactivation of Src, Rac1, and MMP13 by Sal." (PMID 30586948, 2018). "In SW1353 chondrosarcoma cells, it is reported that Rac1 GTPase was suppressed by the elevation of p-eIF2α19." (PMID 28374823, 2017).
ciliopathies (2 papers, 2015 to 2022). "Various studies have shown that ciliopathies, such as Lowe, Joubert, and Bardet-Beidl syndromes, have defects in RhoA or Rac1 localization or activity." (PMID 26044959, 2015). "Mutations in OCRL could therefore cause its ciliopathy by an increase in PIP2, by overactivity of Rac1 and Cdc42, and by impaired endocytosis (impaired endocytosis may trigger ciliary shortening by causing agonist-induced vesicle budding)." (PMID 35079141, 2022).
cone retinal dystrophies (2 papers, 2015 to 2023). "It is therefore possible that the retinal dystrophy and macular hypoplasia that are present in four of our eight patients relate to a loss of Rac1 regulation by HACE1." (PMID 26424145, 2015). "Our observations identify GRF2 and CDC42 (but not RAC1) as key regulators of retinal processes controlling cone photoreceptor nuclear positioning and survival, and support the notion of GRF2 loss-of-function mutations as potential drivers of cone retinal dystrophies." (PMID 37947653, 2023).
congenital nystagmus (2 papers, 2013). Nystagmus present at birth or caused by lesions sustained in utero or at the time of birth. "As the Rac1 signaling pathway appears to be involved in the regulation of neurite extension in the developmental stage, mutations of the FRMD7 gene which alter the regulation of Rac1 signaling may be linked to the pathogenesis of idiopathic congenital nystagmus." (PMID 23967341, 2013).
differentiated thyroid carcinoma (2 papers, 2017 to 2021). Differentiated thyroid carcinoma (DTC), also known as papillary or follicular thyroid carcinoma, is a slow-growing malignancy usually presenting in adults as an asymptomatic thyroid mass. "RAC1b, a hyperactive RAC1 splice variant, has also been detected in several tumor types and seems to correlate with poor clinical outcomes when overexpressed in differentiated thyroid cancers." (PMID 34638434, 2021). "RAC1b is a hyperactive variant of the small GTPase RAC1 and has been recently shown to be overexpressed in a subset of papillary thyroid carcinomas associated with unfavorable outcome." (PMID 28234980, 2017).
diffuse large B-cell lymphoma (2 papers, 2015 to 2022). "In this study, we investigated the expression of FilGAP, with reference to the status of its associated molecules, including FLNa, integrin β2, epithelial cell transforming factor 2 (ECT2), and Rac1, in FL, diffuse large B-cell lymphoma (DLBCL), and peripheral T-cell lymphoma (PTCL)." (PMID 25641953, 2015).
Disc Degeneration (2 papers, 2020 to 2023). "This study was designed to clarify the effect of Rac1 activity in CEP degeneration and disc degeneration and seek for the effective strategy for prevention of IVDD development." (PMID 32040269, 2020). "Collectively, these results provide a strong evidence regarding the protective effect of Rac1 inhibition on CEP and disc degeneration in puncture‐induced rat model." (PMID 32040269, 2020).
Ductal Carcinoma (2 papers, 2010 to 2024). "The observation that ductal carcinoma-specific mutants of CK1ε promote the Wnt/Rac1/JNK and NFAT pathways and, on the other hand, inhibit the Wnt/β-catenin pathway are in good agreement with some clinical observations." (PMID 20507565, 2010). "In summary, our data demonstrate that mutant CK1e, which is present in ductal carcinoma, can act as an inhibitor of the Wnt/β-catenin and an activator of the noncanonical Wnt/Rac1/JNK and Wnt/Ca2+ pathways." (PMID 20507565, 2010).
ductal carcinoma in situ (2 papers, 2010 to 2013). "Based on our findings, we can speculate that the high activity of CK1ε in ductal carcinoma in situ reduces Rac-1/JNK and NFAT activity, keeping the cells tightly attached and blocking tumor invasion." (PMID 20507565, 2010).
E. coli infection (2 papers, 2023 to 2025). "Escherichia coli (E. coli) infection and RAC1 activity are the most significant pathways in KEGG and FunRich pathway analyses, respectively." (PMID 38444712, 2023). "Patients with an E. coli infection typically exhibit high neutrophil counts and Rac1•GTP." (PMID 40041147, 2025). "Also, GO and pathway enrichment analyses identified “pathogenic E. coli infection” in the Kyoto encyclopedia of genes and genomes (KEGG) and “regulation of Rac1 activity” in FunRich as the top pathways." (PMID 38444712, 2023).
fibrosis (2 papers, 2017 to 2024). the formation of excess fibrous connective tissue in an organ or tissue in a reparative or reactive process. "It has been shown that cardiomyocyte-specific Rac1 deficiency reduced ROS production and prevented cardiac fibrosis and hypertrophy in STZ-induced diabetic mice." (PMID 28388570, 2017).
immune deficiency (2 papers, 2017 to 2021). "The importance of these processes for the immune response suggests a possible disease mechanism linking DOCK2 mutations to impaired RAC1 activation and subsequent immune deficiency." (PMID 33893283, 2021). "In humans, Rac2 seems to act dominantly over Rac1 for antibody production since loss of Rac2 or dominant negative Rac2 leads to common variable immunodeficiency with low antibody serum titers." (PMID 29056938, 2017).
influenza (2 papers, 2013 to 2014). An acute viral infection of the respiratory tract, occurring in isolated cases, in epidemics, or in pandemics; it is caused by serologically different strains of viruses (influenzaviruses) designated A, B, and C, has a 3-day incubation period, and usually lasts for 3 to 10 days. "Further development and modification of Rac1 inhibitors might offer even more potent drugs for anti-influenza therapy by targeting Rac1." (PMID 24523909, 2014).
injury (2 papers, 2013 to 2022). Damage inflicted on the body as the direct or indirect result of an external force, with or without disruption of structural continuity. "Astrogliosis was indicated by enrichment of NFAT/calcineurin signaling, which is considered critical for astrocyte activation and Rac1 signaling that has recently been shown to control astrogliosis in the context of brain injury." (PMID 36408415, 2022).
Kaposi ́s sarcoma (2 papers, 2017 to 2022). "Constitutively active Rac1 V12 overexpression-induced tumors in mice were phenotypically similar to human Kaposi’s sarcoma." (PMID 35008419, 2022). "In this sense it would be very interesting to evaluate these inhibitors in Kaposi ́s sarcoma, where Rac1 seems to play an important role in tumorigenesis and it is overexpressed in AIDS-associated Kaposi's Sarcoma lesions." (PMID 29228706, 2017).
kidney failure (2 papers, 2016). An acute or chronic condition that is characterized by the inability of the kidneys to adequately filter the blood. "Cdc42 deletion results in massive neonatal proteinuria, kidney failure, and associated death within 2 weeks of birth, podocyte-specific RhoA and Rac1 deletion mutants are conspicuously healthy." (PMID 26986510, 2016).
Listeria monocytogenes infection (2 papers, 2018). "TNFAIP8 inhibits Ras-related C3 botulinum toxin substrate 1 (RAC1), which regulates bacterial Listeria monocytogenes infections by controlling pathogen invasion and host-cell apoptosis." (PMID 29928491, 2018). "Beyond cancer, the biological role of TNFAIP8 in liver infection has been investigated and the study demonstrated that TNFAIP8 regulates Listeria monocytogenes infection by inhibiting Ras-related C3 botulinum toxin substrate 1 (RAC1)." (PMID 30586922, 2018).
meningioma (2 papers, 2015 to 2023). A generally slow growing tumor attached to the dura mater. "PAK1 inhibition also leads to attenuated mTORC1 but not mTORC2 signaling, suggesting that mTORC2/SGK1 and Rac1/PAK1 pathways are independently responsible for mTORC1 activation in NF2-deficient meningiomas." (PMID 26219339, 2015). "In contrast, inhibition of rac1 or JNK activation abolishes the regulation of cell growth and cyclin A by protein 4.1B, demonstrating that protein 4.1B is a vital cell growth regulator in meningioma cells." (PMID 36835189, 2023).
myelodysplastic syndrome (2 papers, 2019 to 2024). A clonal hematopoietic disorder characterized by dysplasia and ineffective hematopoiesis in one or more of the hematopoietic cell lines. "The miR-155-5p molecule plays a role in the programmed cell death of CD34 + cells in Myelodysplastic Syndromes (MDS) through the RAC1/CREB/miR-15b pathway, thereby suppressing the production of blood cells in the bone marrow." (PMID 38462628, 2024).
Myocardial fibrosis (2 papers, 2021 to 2022). "In T1DM mice, RAC1 deficiency reduced myocardial fibrosis and hypertrophy, resulting in improved myocardial function." (PMID 33560596, 2021). "Further studies have confirmed that Qishen Granules can inhibit the apoptosis of cardiomyocytes, the oxidative stress effect induced by p47phox and RAC1, and myocardial fibrosis." (PMID 36618925, 2022).
Neurodevelopmental delay (2 papers, 2023 to 2024). "Interestingly, a mutation at this residue was reported in an individual diagnosed with moderate neurodevelopmental delays and an associated loss of RAC1 activity was biochemically confirmed." (PMID 38566250, 2024).
Peters anomaly (2 papers, 2024 to 2025). Peters anomaly (PA) is a congenital corneal opacity disorder characterized by a central corneal leukoma that obstructs the pupil leading to visual loss as well as absence of the posterior corneal stroma and Descemet membrane. "This convergent mechanism not only establishes Rac1 as a central therapeutic target but also redefines Peters anomaly pathogenesis through a shared axis of cytoskeletal dysregulation, offering novel insights into its etiology and treatment strategies." (PMID 40060475, 2025). "Our results demonstrate that Abl kinases regulate FGF signaling to balance RhoA and Rac1 activity via the Ptpn12-p130Cas pathway, suggesting that targeting tension-mediated lens vesicle separation could be a therapeutic strategy for Peters anomaly." (PMID 39484567, 2024).
preeclampsia (2 papers, 2021 to 2024). Preeclampsia is a hypertensive disorder of pregnancy that is characterized by new-onset hypertension with proteinuria presenting after 20 weeks of gestation, and depending on mild or severe forms may initially present with severe headache, visual disturbances, and hyperreflexia. "ERAP2, expressed in the placenta, has been linked to the onset and progression of preeclampsia, while RAC1 is involved in regulating placental growth." (PMID 39687015, 2024). "Among these genes, LAMB2, PTK2, RAC1, QSOX1, FN1, and VCAM1 have known associations with the pathogenic mechanisms of preeclampsia." (PMID 35719905, 2021).
retinal vein occlusion (2 papers, 2019 to 2025). An occlusion of the retinal vein. "In the context of retinal hypoxia as seen in diseases like DR, retinal vein occlusion (RVO), and AMD, RAC1 and RAC2 are implicated through several mechanistically relevant pathways." (PMID 40906190, 2025).
retinoblastoma (2 papers, 2014 to 2021). A malignant tumor that originates in the nuclear layer of the retina. "The stronger association of TIAM1 than RAC1 with NE gene expression suggests that in NE SCLC increased expression of select GEFs may lead to increased RAC activity independent of total RAC1 levels, consistent with previous findings in retinoblastoma and nodular melanoma." (PMID 34758330, 2021).
seminoma (2 papers, 2020 to 2025). A radiosensitive malignant germ cell tumor found in the testis (especially undescended), and extragonadal sites (anterior mediastinum and pineal gland). "In contrast, only three non-seminoma tumors showed evidence of pre-WGD driver mutations (three KIT and one RAC1)." (PMID 40568177, 2025). "Association with seminoma was found for mutations in KIT, KRAS and NRAS and for putative oncogenic driver genes CBL, RAC1, PIK3CA, and CTNNB1 (analysed jointly due to lower frequency), p = 3.33 × 10−10, p = 1.41 × 10−6, p = 0.002, p = 0.009, respectively." (PMID 32366847, 2020).
squamous intraepithelial lesions (2 papers, 2020 to 2025). "Nuclear localization of Rac1 was found in low-grade squamous intraepithelial lesions (LSIL) and high-grade squamous intraepithelial lesions (HSIL), as well as in tumor cells SiHA (HPV-16 infected) and C33A (HPV-negative)." (PMID 32443784, 2020).
synucleinopathies (2 papers, 2020 to 2024). "This is the first study showing that miR-124-3p decreases PQ-induced α-synuclein levels and the associated NOX1/Rac1 signaling pathway, and impacts PITX3 protein levels, supporting the potential of miR-124-3p as a disease-modifying agent for PD and related α-synucleinopathies." (PMID 38451434, 2024). "Future studies to analyze in depth the effect of miR-124-3p in p47phox, p67phox and Rac1 activation will allow to discriminate the modulatory effect on the NOX1 signaling pathway and indirectly in α-synucleinopathy." (PMID 38451434, 2024).
tetanus (2 papers, 2022 to 2024). A serious infectious disorder that follows wound contamination by the Gram-positive bacterium Clostridium tetani. "Finally, acute inhibition of the Vav-Rac1 pathway efficiently reduces RP mobilization, causing alterations in tetanus-induced plasticity: reduced PTP under low Ca2+ and enhanced depression under high Ca2+." (PMID 35976098, 2022). "Interfering with the Vav-Rac1-SCAR pathway also impairs mobilization of reserve pool (RP) vesicles required for tetanus-induced synaptic plasticity." (PMID 35976098, 2022). "Having found that Vav plays important roles in RP mobilization and PTP, we next examined whether these tetanus-induced processes also require the Rac1-SCAR cascade." (PMID 35976098, 2022).
tuberculosis (2 papers, 2022 to 2024). A chronic, recurrent infection caused by the bacterium Mycobacterium tuberculosis. "The bacillus Calmette–Guerin (BCG) vaccine for tuberculosis (TB) has been shown to be effective in the treatment of bladder cancer by macropinocytic delivery, which is dependent on RAC1, CDC42, and its effector PAK1." (PMID 39000072, 2024).
ulcerative colitis (2 papers, 2012 to 2018). An inflammatory bowel disease involving the mucosal surface of the large intestine and rectum. "Rac1 gene, which was increased by HSD, has been associated with ulcerative colitis in many studies." (PMID 29566748, 2018).
Ventricular arrhythmia (2 papers, 2016 to 2025). "Cardiomyocyte-specific Rac1 knockdown mice as well as mice treated with NSC23766 are protected against ventricular arrhythmia after I/R which is thought to be due to decreased Ca2+ release from the sarcoplasmic reticulum (SR)." (PMID 41333012, 2025). "In summary, this study showed that myocardial I/R activates Rac1 and induces ventricular arrhythmia." (PMID 27222313, 2016). "Adult Rac1f/f and cardiac‐specific Rac1 knockdown (Rac1ckd) mice were subjected to myocardial I/R and their electrocardiograms (ECGs) were monitored for ventricular arrhythmia." (PMID 27222313, 2016). "Myocardial Rac1 activity was increased and ventricular arrhythmia was induced during I/R in Rac1f/f mice." (PMID 27222313, 2016). "Collectively, these results suggest that activation of Rac1 in the heart contributes to ventricular arrhythmia during myocardial I/R." (PMID 27222313, 2016). "The major finding of this study is that inhibition of Rac1 protects against ventricular arrhythmia during myocardial I/R." (PMID 27222313, 2016). "We suggested that Rac1 is activated during myocardial I/R and inhibition of Rac1 protects against ventricular arrhythmia during I/R." (PMID 27222313, 2016). "Rac1 has also been studied for its role in ventricular arrhythmias." (PMID 41333012, 2025). "We conclude that Rac1 activation induces ventricular arrhythmia during myocardial I/R." (PMID 27222313, 2016). "However, the role of Rac1 in cardiomyocyte Ca2+ handling and ventricular arrhythmia during myocardial I/R remains elusive." (PMID 27222313, 2016). "In this study, we hypothesized that inhibition of Rac1 protects against ventricular arrhythmia during myocardial I/R through decreases in ROS, RyR2 oxidation and SOICR." (PMID 27222313, 2016). "However, how Rac1 disrupts Ca2+ homeostasis and promotes ventricular arrhythmia in the ischaemic heart remains elusive." (PMID 27222313, 2016). "Furthermore, treatment with Rac1 inhibitor NSC23766 decreased I/R‐induced ventricular arrhythmia." (PMID 27222313, 2016). "Our data show for the first time that inhibition of Rac1 suppresses SOICR and protects against ventricular arrhythmia during myocardial I/R." (PMID 27222313, 2016). "We aimed to study the effects of Rac1 inhibition on store overload‐induced Ca2+ release (SOICR) and ventricular arrhythmia during myocardial I/R." (PMID 27222313, 2016). "Our results demonstrated that Rac1 promotes the occurrence of SOICR in cardiomyocytes, which induces ventricular arrhythmia." (PMID 27222313, 2016). "Our study suggests that Rac1 activation contributes to RyR2 oxidation, SOICR and ventricular arrhythmia during myocardial I/R." (PMID 27222313, 2016). "Inhibition of Rac1 suppresses SOICR and protects against ventricular arrhythmia." (PMID 27222313, 2016).
viral myocarditis (2 papers, 2023 to 2024). Myocarditis that is caused by an infection with a viral agent. "We observed a significant enrichment in terms associated with viral myocarditis (KEGG Pathway hsa05416) and leukocyte transendothelial migration (KEGG Pathway hsa04670), illustrated by the positive regulation of several genes from the cytoskeleton (actin, coronin 1A, RAC1...)." (PMID 39185406, 2024).
abdominal aortic aneurysm (1 paper, 2023). Enlargement and ballooning of the vessel that supplies arterial blood to the abdomen, pelvis and legs. "In contrast, the inhibition of RAC1 can significantly inhibit the activation of NF-κB and lead to decreased expression of MMP-9, MCP-2 and CXCL5 in abdominal aortic aneurysm tissue." (PMID 36835806, 2023).
acral melanoma (1 paper, 2022). "Notably, the high expression levels of RAC1 also predicted worse OS in our acral melanoma cohort." (PMID 35534866, 2022).